PDHA1 (pyruvate dehydrogenase E1 subunit alpha 1)
Diseases named in the same sentence as PDHA1 in open-access papers (continued):
Sharing a sentence is not in itself a finding about the gene and the disease.
cancer (continued). "PDHA1, the PDHC’s active regulatory site The cuproptosis-related gene PDHA1 is crucial for the metabolic transformation of cancer as it regulates the cuproptosis process." (PMID 38023234, 2023). "Based on previous findings of the key role of PDHA1 in NB pathogenesis, this study further explored its role in pan-cancer." (PMID 38012558, 2023). "In summary, by performing a comprehensive pan-cancer analysis of PDHA1, we displayed the abnormal expression profiles of PDHA1 and its correlation with clinical prognosis and immune response." (PMID 36003495, 2022). "Emerging studies have demonstrated that cancer metabolism regulated by PDHA1 plays a key role in cancer progression and metastasis." (PMID 36003495, 2022). "p-PDHA1 is increased in a variety of cancer types, and this is mediated by several types of PDH kinases (PDKs) overexpressed in numerous cancers." (PMID 35740278, 2022). "As for the PDHA1 gene, there have been many reports that it has a significant prognostic value and clinical significance in various cancers." (PMID 36117848, 2022). "This study further illustrates the significance of the expression of DLAT, DLST, GLS, and PDHA1 for cancer treatment." (PMID 36588699, 2022). "Our study showed that the PDHA1 expression was negatively correlated with CAFs, DCs, B cells, and T cells in many cancers." (PMID 36003495, 2022). "In drug sensitivity analysis, the expression of CDKN2A, DLAT, PDHA1, and GLS was negatively associated with some or most drugs in the Cancer Therapy Response Portal database, and the expression of DLST positively correlated." (PMID 36588699, 2022). "In our study, a pan-cancer analysis was performed to explore the role and mechanism of PDHA1 in 33 human cancer types." (PMID 36003495, 2022). "Decreased expression of PDHA1 was found to be an unfavorable prognostic factor in various types of cancer including ovarian, gastric, prostate, lung, liver, and esophageal cancer." (PMID 35083212, 2021). "Taken together, these results demonstrate that PDHA1 is tyrosine-phosphorylated in cancer cells in a Src-dependent manner." (PMID 26848621, 2016). "Taken together, these results suggest that Src-mediated metabolic regulation through PDHA1 Y289 phosphorylation promotes cancer cell's resistance to pro-oxidant chemotherapy." (PMID 26848621, 2016). "Although we found that AURKA, as a ferroptosis-related gene, may be associated with cuproptosis-related genes such as DBT, DLST, LIAS, and PDHA1, how they interact with each other to influence cancer development needs to be investigated in depth." (PMID 38673957, 2024). "DLAT is the initiator of the TCA cycle, and overexpressed DLAT promotes glycolysis and inhibits the breakdown of pyruvate into acetyl-CoA instead of promoting the TCA cycle, thereby aggravating the malignant development of NSCLC; PDHA1 plays a role in HCC cancer metastasis and clinical pathology." (PMID 38078880, 2023). "The decrease in IL-6 secretion by the adipocytes upon inhibition of SHP2, PDHA1 or ROS also suggests that the SHP2-PDHA1-ROS axis might regulate inflammation in the adipose tissue, and thereby indirectly influences cancer progression." (PMID 36074246, 2023). "There is a complex relationship between the PDHA1 gene and cancer." (PMID 37006250, 2023). "Nevertheless, the detailed roles of PDHA1 in various cancers remain largely unclear." (PMID 36003495, 2022). "In drug sensitivity analysis and immune checkpoint analysis, the results showed that CDKN2A, DLAT, PDHA1 and GLS were negatively associated with some or most drugs in the cancer therapeutic response portal database, and the expression of DLST was positively correlated." (PMID 36588699, 2022). "We found that PDHA1 was aberrantly expressed in most cancer types." (PMID 36003495, 2022). "In gastric cancer, downregulated PDHA1 promoted cancer progression by increasing glycolysis." (PMID 36003495, 2022).
cancer (continued). "In addition, Liu and his colleagues suggested that PDHA1 participates in the activation of glycolysis and fosters cancer cell viability by binding with miR-21-5p." (PMID 35342421, 2022). "PDHA1 has been shown to be either beneficial or detrimental in a cancer type-specific manner." (PMID 36497253, 2022). "In addition, we also analyzed the protein phosphorylation and methylation values of PDHA1 in a variety of human cancers." (PMID 36003495, 2022). "Based on Src's ability to induce PDHA1 tyrosine phosphorylation, we verified whether PDHA1 was tyrosine-phosphorylated in Src-activated cancer cells." (PMID 26848621, 2016). "We stably expressed the Src-resistant PDHA1 Y289F mutant in Src-activated cancer cells through lentiviral transduction, and examined whether it reversed Src's effect on metabolism and cell proliferation/survival." (PMID 26848621, 2016). "This could be corroborated by our proteomics functional analysis, where we found, for instance, a higher abundance of HADH, PLOD3 and ACAT1 (lysine degradation) and PFKL, NTRK1, PDHB and PDHA1 (central carbon metabolism in cancer) in control piglets compared to UL." (PMID 38409238, 2024). "In addition, these miRNAs may also target SCO2 and PDHA1 and promote glucose metabolism in favor of cancer progression." (PMID 37583933, 2023). "In addition, PDHA1 also played a critical role in cancer chemoresistance." (PMID 36003495, 2022). "Therefore, PDHA1 is considered a key target for anti-cancer therapy." (PMID 36211401, 2022). "We next asked whether PDHA1 tyrosine phosphorylation in these cancer cells was dependent on Src." (PMID 26848621, 2016). "Indeed, Src was the main kinase responsible for PDHA1 tyrosine phosphorylation in cancer cells." (PMID 26848621, 2016). "Here, we uncover a previously undescribed mechanism by which YBX1 regulates PDHA1 activity and the role of the YBX1–PDHA1 axis in cancer cells." (PMID 40812419, 2025). "In this pan-cancer analysis, we systematically profiled the expression and prognostic value of eight well-characterized cuproptosis-related genes—FDX1, LIAS, LIPT1, DLD, DLAT, PDHA1, PDHB, and SLC31A1—across 34 cancer types." (PMID 40601654, 2025). "Since PDHA1 acetylation was previously reported, we focused on exploring the role of PDHX acetylation in cancer cells." (PMID 39311688, 2025). "The prognostic model incorporates genes, such as YY2, PDHA1, SDC3, PPP2CB, and PDK3, all of which have been previously reported to influence cancer prognosis." (PMID 41235100, 2025). "In Cuproptosis-related genes, SPC25 was positively correlated with GCSH, CDKN2A, PDHB, PDHA1, DLAT, DLD, and SLC31A1 of pan-cancer." (PMID 38605119, 2024). "Combined with 19 genes related to cuproptosis in the current cancer database, NFE2L2, PDHA1, PDHB, DLD, and GLS showed significant differences between the two groups." (PMID 38200445, 2024). "A total of 6 CRSGs were screened out, including CDKN2A, GLS, FDX1, PDHA1, PDHB, and DLD; most of them have been reported in the direct regulation of cuproptosis and cancer progression." (PMID 37287976, 2023). "In contrast, eight regulators (PDHA1, ATP7A, LIPT1, LIPT2, GLS, ATP7B, GCSH, and CDKN2A) were upregulated in cancer tissues." (PMID 36672336, 2023). "As part of the pyruvate dehydrogenase enzyme complex, PDHA1 links glycolysis with the TCA cycle and plays an important role in cancer metabolism." (PMID 36313439, 2022). "The results showed that cuproptosis-related genes such as PDHB, PDHA1, DLAT, DLD, LIPT1 were significantly positively correlated with FDX1 in pan-cancer." (PMID 35991547, 2022). "Pyruvate dehydrogenase E1 subunit alpha 1, a component of the pyruvate dehydrogenase enzyme complex, links glycolysis and the TCA cycle and is important for cancer metabolic shift." (PMID 35742953, 2022). "We found that the expression of PDHA1, GLS, DLAT, PDHB and MTF1 were differed between cancer and paracancer." (PMID 36620594, 2022).
cancer (continued). "Moreover, PDHA1 may be a prognostic and immune-related biomarker in a variety of cancers." (PMID 36211401, 2022). "p-PDHA1, which reduces PDH activity, is critical for increased lactate and other intermediate metabolites during glycolysis and is used for cancer cell growth, which is called aerobic glycolysis or the Warburg effect." (PMID 35740278, 2022). "In this study, we showed that IQ suppressed the growth of several types of cancer cells by inhibiting the kinase activity of PDK1 by interfering with ATP binding, subsequently dephosphorylating and activating PDHA1." (PMID 32825675, 2020). "DLD and DLAT have the highest correlation in pan-cancer, followed by DLD and PDHA1." (PMID 36845390, 2023). "There were positive and negative correlations of FDX1 and PDHA1 with CD8+ T cell infiltration found in pan-cancers, while there were two negative correlations for TCGA-STAD." (PMID 36895378, 2023). "In conclusion, the downregulation and kinase activity of PDHA1 may function with the PI3K-Akt-mTOR pathway in some way, which could suppress the cuproptosis level and account for the cancer-like pathology in EMs." (PMID 36474131, 2023). "Furthermore, we conducted the correlation analysis in pan-cancer, and the result demonstrated that DLD and PDHA1 were the two genes having the most significantly positive association (Correlation coefficient = 0.39)." (PMID 36518756, 2022). "Although a number of studies have highlighted the significance of PDH activity or PDHA1 to promote metabolism and growth in cancer cells, the relationship between PDH and EMT has not been elucidated." (PMID 35083212, 2021). "In addition, these miRNAs may also target key regulators of glucose metabolism, such as synthesis of cytochrome C oxidase 2 (SCO2) and pyruvate dehydrogenase alpha 1 (PDHA1), in favor of cancer progression." (PMID 37583933, 2023). "Finally, the data on the gene expression profiles of cancer cell lines were integrated in the Genomics of Drug Sensitivity in Cancer (GDSC) database for drug sensitivity to fully explore the potential value of CDKN2A, DLAT, DLST, GLS, and PDHA1 genes as novel therapeutic targets." (PMID 36891150, 2023). "Indeed, only modulating PDHA1 expression is not sufficient to explain how it drives the aggressiveness of cancer cells." (PMID 37056926, 2023). "In many cancers, highly expressed pyruvate dehydrogenase kinase 1 (PDK1) reduces the activity of pyruvate dehydrogenase (PDH) by inducing the phosphorylation of its E1α subunit (PDHA1) and subsequently, shifts the energy metabolism from OxPhos to aerobic glycolysis." (PMID 32825675, 2020). "We demonstrated that PDHA1 gene KO significantly decreased mitochondrial OXPHOS and promoted anaerobic glycolysis, accompanied with higher stemness phenotype including resistance to chemotherapy, enhanced migration ability and increased expression of cancer stem cell markers." (PMID 28076853, 2017). "Expression of a tyrosine-289 non-phosphorable PDHA1 mutant in Src-hyperactivated cancer cells restored PDH activity, increased mitochondrial respiration and oxidative stress, decreased experimental metastasis, and sensitized cancer cells to pro-oxidant treatment." (PMID 26848621, 2016). "No obvious changes in methylation values of PDHA1 could be found in other cancers." (PMID 36003495, 2022).
infection (9 papers, 2008 to 2025). The state of being infected such as from the introduction of a foreign agent such as serum, vaccine, antigenic substance or organism. "While the microarray data showed that expression of the pyruvate dehydrogenase (Pdh) complex genes was not significantly changed, the data obtained by qPCR showed a downregulation of Pdha1 expression during the first 12 hours post infection (hpi)." (PMID 22928052, 2012). "(F) Immunoblotting of host glycolytic (PGK), TCA cycle (PDHA1), and fatty acid oxidation (HADHA, ACOX-1) proteins under Sirt1 and Sirt3 knockdown condition of S. Typhimurium-infected RAW 264.7 macrophages at 16 hr post-infection." (PMID 39693143, 2024).
neurodegenerative disease (2 papers, 2019 to 2021). A disorder of the central nervous system characterized by gradual and progressive loss of neural tissue and neurologic function. "However, the exact role of PDHA1 deficiency in neurodegenerative diseases remains to be elucidated." (PMID 34720870, 2021). "Numerous studies demonstrated that low expression of proteins such as Aldoa, Pdha1, and Car2 was found in neurodegenerative diseases including AD, PD, and Lewy Body." (PMID 30935111, 2019).
digestive diseases (1 paper, 2022). "The four overlapping genes, including LIAS, DLAT, DBT, and PDHA1, were dysregulated expressed in the interaction between the four digestive diseases using the Venn diagram." (PMID 36405733, 2022).
peripheral neuropathy (1 paper, 2022). A disorder affecting the peripheral nervous system. "In 3–21% of patients, peripheral neuropathy has been found to be linked to PDC deficiencies, whereas progressive peripheral neuropathy in adult patients has been linked only to mutations in PDHA1." (PMID 35235001, 2022).
PDHA1 also shares sentences with these, for which no sentence is quoted: mitochondrial disease (5 papers); acute kidney injury (3); Hyperglycemia (3); Intellectual disability (3); Rett syndrome (3); Alzheimer disease (2); celiac disease (2); Cerebral ischemia (2); colon (2); Crohn disease (2); Encephalopathy (2); lymphoid neoplasm (2); Parkinson disease (2); renal cell carcinoma (2); thymoma (2); thyroid cancer (2); acute lymphoblastic leukemia (1); acute myeloid leukemia (1); adenocarcinoma (1); Alexander disease (1); Barth syndrome (1); biotinidase deficiency (1); bone cancer (1); brain cancer (1); breast invasive carcinoma (1); breast tumor (1); Cerebral atrophy (1); cognitive (1); colon cancer (1); congenital cataracts (1).
A further 59 diseases each share a sentence with PDHA1 in 1 paper.